ENSG00000276393 (nuclear receptor subfamily 3, group C, member 1 (glucocorticoid receptor) (NR3C1) pseudogene)
Synonyms: GCR2; GCRL; GRLL1; NR3C1P; NR3C1P1
Gene: Unprocessed pseudogene on chromosome 16 (87,467,138 to 87,467,654, forward strand). Ensembl gene ENSG00000276393.
Diseases named in the same sentence as ENSG00000276393 in open-access papers:
ENSG00000276393 is named in the same sentence as 1 disease in open-access papers, as found by Europe PMC text mining. Sharing a sentence is not in itself a finding about the gene and the disease.
ENSG00000276393 shares sentences with these, for which no sentence is quoted: skeletal disease (1 paper).